DNMT1 (DNA methyltransferase 1)
Diseases named in the same sentence as DNMT1 in open-access papers (continued):
Sharing a sentence is not in itself a finding about the gene and the disease.
lymphoma (37 papers, 2006 to 2025). A malignant (clonal) proliferation of B- lymphocytes or T- lymphocytes which involves the lymph nodes, bone marrow and/or extranodal sites. "For instance, since low expression of DNMT1 can reduce 5mC to about 10% of the normal level, DNMT1–deficient mice are more prone to suffer aggressive lymphoma and chromosomal instability." (PMID 36045397, 2022). "6-TG has been shown to be epigenetically active as a demethylating agent in a human lymphoma cell line, causing downregulation of DNA methyltransferase 1 (DNMT1) through ubiquitin-targeted degradation." (PMID 25480665, 2014). "In terms of survival prediction using different DNMT expressions, previous studies showed that overexpression of DNMT1 or DNMT3b was associated with a poor prognosis in cancers of the lung, liver, and pancreas, lymphoma and other malignancies." (PMID 22768205, 2012). "The hypothesis of the present study was that 6-TG and Zeb would cause downregulation of DNMT1 and globally demethylate the genomic DNA of canine lymphoma cells." (PMID 25480665, 2014). "For instance, RIP-Seq analysis in lymphoma cells indicated that nuclear eIF4E binds over 3000 mRNAs that encode proteins acting in lymphoma-sustaining pathways such as B-cell receptor signaling (Bcl2, Bcl6) and DNA methylation/epigenetic regulation (DNMT1, DNMT3A, HDAC1)." (PMID 30455716, 2018). "At the cellular level, suppression of DNMT1 hinders the cellular proliferation, formation of cell colonies and progression of the cell cycle while also triggering apoptosis in lymphoma cells." (PMID 40387409, 2025). "DNMT1 is essential in several lymphomas, and particularly in diffuse large B-cell lymphomas, where it is commonly expressed and promotes cell cycle progression and DNA replication." (PMID 40299416, 2025). "In this manner, miR‐152 exerts an inhibitory effect on lymphoma growth through its capacity to suppress the DNMT1‐mediated silencing mechanism of SOCS3 and SHP‐1." (PMID 40387409, 2025). "Epigenetic alterations in lymphoma include those involved in DNA methylation (e.g. DNMT1), histone acetylation (e.g. CREBBP), histone methylation (e.g. EZH2) and non-coding RNA (e.g. miR-155)." (PMID 37869076, 2023). "Even though DNMT1 and DNMT 3B are the most frequently overexpressed and mutated DNMTs in lymphoma, DNMT 3A has been found to be mutated in nearly 11–20% of patients with T-cell lymphoma." (PMID 35326620, 2022). "Among them, miR-152 indirectly promotes PTPN6 expression to suppress lymphoma growth through down-regulation of DNA methyltransferase 1 (DNMT1)." (PMID 35957898, 2022). "Abnormal expression of DNMT1 and DNMT3β has been reported in several tumours, including lung, liver, breast, ovarian, colorectal, meningiomas and lymphomas.Reduced expression of CIITA was observed in PBMCs but not in BM." (PMID 26466379, 2015). "The data showed that DNMT1 expression was positively correlated with age of the patients, i.e., DNMT1 protein was expressed more in older patients, the data of which were consistent with that of lymphoma." (PMID 22768205, 2012). "DNMT1 and DNMT3B are the most frequently overexpressed and mutated DNMTs in lymphomas." (PMID 40299416, 2025). "Our previous work in T-lymphoma cells demonstrated that GlyCl can also impair DNA methylation by directly inhibiting DNMT1 activity and other studies have shown that DNMT activity is a requirement for murine CD8+ T cell proliferation and effector phenotype differentiation." (PMID 38899429, 2024). "In summary, 5-Aza-2’ and TAK981 have potential to synergistically inhibit tumor cell growth and UBC9 and DNMT1 expression could be potential biomarkers for sensitivity of lymphomas for the combination therapy." (PMID 36792656, 2023). "Our data revealed that N3a-treatment may directly lead to increase in the master epigenetic conductor UHRF1 and its privileged partner DNMT1, over-expressed in different cancer types and lymphomas, promoting cell growth inhibition." (PMID 37568720, 2023).
lymphoma (continued). "Interestingly, upregulation of DNMT1 has been shown to correlate with inferior survival in NHL, hence implicated in the pathogenesis of lymphoma." (PMID 33076962, 2020). "It has been shown that STAT3 increases the content of DNMT1 in malignant T-lymphoma cells." (PMID 28528402, 2017). "In TNBC, MALAT1 inhibits DNA methyltransferase 1 (DNMT1) expression by acting as a sponge for miR-137, inducing B-Cell CLL/Lymphoma 11A (BCL11A) expression, a zinc-finger transcription factor." (PMID 41181715, 2025). "Downregulation of DNMT1 by shRNA inhibited proliferation, cell cycle and clonal formation, as well as induced apoptosis in OCI-Ly10 and Granta-159 lymphoma cell lines." (PMID 35326620, 2022). "Unlike DNMT3A/B, DNMT1 levels did not seem to be changed in lymphomas (data not shown)." (PMID 38464090, 2024).
osteosarcoma (35 papers, 2014 to 2025). A usually aggressive malignant bone-forming mesenchymal neoplasm, predominantly affecting adolescents and young adults. "lncRNA NEAT1 (nuclear enriched abundant transcript 1) epigenetically suppresses E-cadherin expression in osteosarcoma cells by association with the G9a–DNMT1 (DNA methyltransferase 1)—SNAIL complex." (PMID 31947678, 2020). "Furthermore, overexpression of miR-139 can suppress osteosarcoma cell growth, and loss of miR-139 can promote cell proliferation by regulating DNMT1." (PMID 36833394, 2023). "In the osteosarcoma model, isovitexin further induced apoptosis and caused epigenetic regulation through the DNA methyltransferase 1 (DNMT1)/miR-34a/Bcl-2 axis, causing the suppression of stemness and inducing apoptosis in the spheres derived from osteosarcoma cells." (PMID 32708138, 2020). "This silencing is driven by DNMT1 (DNA methyltransferase 1)‐mediated DNA hypermethylation in osteosarcoma cells." (PMID 41357670, 2025). "By targeting DNMT1 and modulating miR-34a expression, isovitexin effectively hampers cancer stemness properties and induces apoptosis in osteosarcoma cells." (PMID 37835417, 2023). "Recent studies suggest DNMT-1 inhibition can enhance the sensitivity of osteosarcoma cells to specific agents like cabozantinib." (PMID 38140058, 2023). "In human osteosarcoma cells, the DNMT1/miR-34a axis has been found to play a major role in the maintenance of the osteosarcoma stem cells, leading to the development of tumours." (PMID 35838271, 2022). "In osteosarcoma, HOTAIR was found to positively regulate the global DNA methylation level and specifically DNMT1 expression, making it an interesting diagnostic marker and therapeutic target." (PMID 35755302, 2022). "In fact, studies focused on DNA methylation pattern for drug repurposing in osteosarcoma identified a significant increase in DNMT1-dependent chemosensitivity toward Cisplatin therapies when treated with Decitabine (DNMT inhibitor)." (PMID 35755302, 2022). "Consistently, overexpression of DNMT1 reduced the expression of miR-34a and promoted the expression of stemness markers in osteosarcoma stem-like cells." (PMID 35252166, 2022). "Mechanistic study showed that isovitexin reduced DNMT1 expression and activity, upregulated miR-34a and attenuated the expression of Bcl-2 in osteosarcoma sphere cells." (PMID 35252166, 2022). "In contrast, in the context of DNMT1 inhibition in osteosarcoma, activation of the CXCL12-CXCR4 axis reduced metastasis and promoted T cell recruitment." (PMID 30873179, 2019). "We observed that HDAC1 and DNMT1 expressions remained similar independently by treatments indicating that they have no key role in the processes of acetylation and methylation in osteosarcoma." (PMID 30509303, 2018). "Nevertheless, it is undefined as to whether the mechanism of its action in osteosarcoma (OS) is connected with epigenetic regulation or if it involves microRNAs, DNA methyltransferase 1 (DNMT1), or their targets." (PMID 36984844, 2023). "In addition to these, the alteration in the methylation patterns (by binding DNMTs, e.g., DNMT1, DNMT3A, and DNMT3B) mediated by lncRNAs have also been associated with the pathogenesis and progression of osteosarcoma." (PMID 35755302, 2022). "Prompted by the evidence that 1 decreased DNMT expression in primary osteosarcoma cells, and 4 phenocopied similar effects in HCT116 and PC-3 cells, we tested selected compounds 2b and 4c as representative samples of the 2 and 4 series to study their effects on DNMT1 and DNMT3A protein expression." (PMID 32075099, 2020). "Interestingly, another study showed that DNMT1 inhibitor treatment induced expression of CXCL12 in osteosarcoma tumors." (PMID 30873179, 2019). "Notably, the DNMT1/miR-34a/Bcl-2 axis has emerged as a key regulatory pathway in osteosarcoma." (PMID 37835417, 2023).
osteosarcoma (continued). "Another study reported that Isovitexin could suppress the features of human osteosarcoma stem-like cells by interfering with the DNMT1/miR-34a/Bcl-2 axis, which provides a clearer mechanism of apoptotic cell death induced by Isovitexin and is crucial to explore the causes of chemoresistance." (PMID 35838271, 2022). "In osteosarcoma, epigenetically downregulated CXCL12 via DNA methyltransferase 1 (DNMT1) impairs CD8 + killer T cell homing to the tumour sites, consequently, metastatic cells evade immune mediated cytotoxicity." (PMID 40442778, 2025). "CRISPR/Cas9 knockout of DNMT1 using sgRNA had a more negative impact on the growth of a synovial sarcoma cell line (HS-SY-II) compared with an osteosarcoma cell line (KHOS)." (PMID 40299558, 2025).
diabetes (34 papers, 2012 to 2025). "Consistent with the idea of a GD hematopoietic memory, these results show that offspring born to diabetic pregnancy maintain into adulthood high expression of DNMT1, a molecular feature associated with overt diabetes." (PMID 37988162, 2024). "Another study has found that inhibiting DNA methyltransferase 1 (DNMT-1) can alleviate ferroptosis through nuclear receptor coactivator 4 (NCOA4) mediated ferritinophagy during diabetes myocardial IRI." (PMID 38076182, 2023). "This study aimed to explore the correlation between the relative expression levels of peripheral blood α1-MG, DNMT1 and the extent of renal pathology in DN patients by comparing them with patients with simple diabetes." (PMID 37861555, 2023). "The results indicated that exogenous H2S decreased the DNMT1 protein level in the endothelial cells that were up-regulated (induced by diabetes)." (PMID 36078059, 2022). "Key parameters were confirmed in an in vivo model using retinal microvessels from mice, that were administered Suv39H1-siRNA or Dnmt1-siRNA (intravitreally) soon after induction of streptozotocin-induced diabetes." (PMID 34238980, 2021). "We demonstrate that diabetes increases the recruitment of Suv39H1 at Rac1 promoter, which assists in the recruitment of Dnmt1, initiating an active DNA methylation-hydroxymethylation and transcriptional activation." (PMID 34238980, 2021). "In the same group of rats, Dnmt1-siRNA administration also attenuated diabetes-induced increase in Dnmt1 gene transcripts." (PMID 32313015, 2020). "Re-institution of good glycemic control, soon after induction of diabetes in rats (GC group), however, protected hypermethylation of Mfn2 and Mlh1 promoter DNA, and along with the binding of Dnmt1, prevented decrease in their gene transcripts." (PMID 32313015, 2020). "In diabetes, the binding of both Dnmt1 and Tet2 is increased at its promoter, suggesting an active methylation-hydroxymethylation process of the Rac1 promoter." (PMID 31277234, 2019). "In diabetes, enzyme activities of both Dnmts and Tets are increased in the retina and its vasculature, and among these two families of enzymes, Dnmt1 and Tet2 are the only respective isoforms that are upregulated." (PMID 31277234, 2019). "Despite increased recruitment of DNA methyltransferase 1 (Dnmt1) at the MMP-9 promoter in diabetes, our results have shown that 5 methyl cytosine (5mC) levels are decreased." (PMID 29261844, 2017). "Mouse models with diabetes displayed higher DNA methyltransferase 1 (DNMT1) levels." (PMID 36787250, 2023). "However, in the condition of diabetes, myocardium with I/R injury possesses a higher level of ferroptosis, ferritinophagy, and DNMT-1." (PMID 34588431, 2021). "In conclusion, inhibition of DNMT-1 could reduce ferroptosis during diabetes myocardial IRI and the NCOA4-mediated ferritinophagy may participate in the process." (PMID 34588431, 2021). "Whether DNMT-1 can affect ferroptosis through NCOA4 is worthy of further study in the process of diabetes myocardial IRI." (PMID 34588431, 2021). "However, supplementation with Aza or Dnmt1-siRNA, during the good glycemic phase, which had followed poor glycemia, or soon after induction of diabetes, ameliorated retinal pathology." (PMID 32313015, 2020). "Several reports have highlighted the pivotal role played by key epigenetic modifiers, such as DNA methyl transferase 1(Dnmt1) during pancreatic development and how their dysregulation may lead to diabetes progression." (PMID 33217903, 2020). "Similarly, in mouse retinal microvessels, Dnmt1-siRNA ameliorated diabetes-induced increase in Rac1 transcripts and activity, and decreased ROS levels." (PMID 30347077, 2018). "In a preliminary analysis, we evaluated variables that might have a potential impact on DNMT1 and DNMT3B expression, including dietary and lifestyle habits, haematological parameters, and cardiovascular or diabetes risk factors." (PMID 27169697, 2016).
diabetes (continued). "Next, we used a mouse model of T2D to further elucidate the role of DNMT1 in diabetes." (PMID 27322146, 2016). "From our results, expression of Dnmt1 decreased in oocytes from both diabetes models, indicating that diabetes may threaten normal imprint of the mouse genome." (PMID 22911868, 2012). "The results of this study showed that the relative expression levels of peripheral blood α1-MG, DNMT1, and VEGF were higher in DN patients compared to patients with simple diabetes." (PMID 37861555, 2023). "The purpose of this study was to investigate whether inhibition of DNA (cytosine-5)-methyltransferase 1 (DNMT-1) alleviated ferroptosis through nuclear receptor coactivator 4 (NCOA4)-mediated ferritinophagy during diabetes myocardial (DM) ischemia/reperfusion (I/R) injury (IRI)." (PMID 34588431, 2021). "Other research suggested that regardless of the type of diabetes, a high glucose condition can induce ROS and impair the balance of DNMT1 expression; however, curcumin can restore the activity and expression of DNMT1, which protects RPE from oxidative stress." (PMID 33379248, 2020). "Similarly, reinstitution of good control after 3 months of poor control in rats did not reverse diabetes-induced increase in retinal Dnmt1 and Tet2, and alter the methylation status of mtDNA and MMP-9." (PMID 27787562, 2016).
non-small cell lung carcinoma (34 papers, 2008 to 2025). A group of at least three distinct histological types of lung cancer, including non-small cell squamous cell carcinoma, adenocarcinoma, and large cell carcinoma. "The lncRNA MIR210HG promotes the proliferation and invasion of non-small cell lung cancer by binding to DNMT1 directly, thereafter upregulating methylation of the CACNA2D2 promoter." (PMID 38784389, 2024). "The mRNA levels of DNMT1 and DNMT3b are elevated in more than 50% of patients with non-small cell lung cancer (NSCLC)." (PMID 36959680, 2023). "For example, in non-small-cell lung cancer, miR-148a-3p forms a regulatory pathway with DNA methyltransferase 1 (DNMT1) to increase tumor proliferation." (PMID 33441699, 2021). "DNA methyltransferase 1 (DNMT1) which is reported to be overexpressed in response to cigarette smoke in non-small cell lung carcinoma and was found significantly overexpressed (1.9 fold overexpressed; p-value ≤ 0.05) in smoke exposed cells." (PMID 29728663, 2018). "UHRF1 was also shown to be overexpressed in primary non-small cell lung cancer (NSCLC) and its high expression level was associated with an increase in the expression of DNMT1, DNMT3A, and DNMT3B and correlated with hypermethylation of p16INK4A promoter." (PMID 27839516, 2016). "G9a and DNMT1 by CM272 severely reduce methylation of SCARA5 and AOX1promoter and increase the efficacy of non-small cell lung cancer (NSCLC)." (PMID 39996888, 2025). "In non-small-cell lung cancer, HOXA11-AS guides EZH2 and DNMT1 proteins to the promoter region of miR-200b and blocks miR-200b transcription." (PMID 31757938, 2019). "In this study, we measured the mRNA expression levels of three methylation-regulating genes (DNMT1, DNMT3b, and MBD2) in 148 tumour samples from patients with non-small cell lung cancer (NSCLC) using quantitative real-time polymerase chain reaction and then determined their prognostic values." (PMID 18414412, 2008). "We sequenced KRAS and investigated expression of NQO1 and five clinically relevant proteins (DNMT1, DNMT3a, ERK1/2, c-MET, and survivin) in 108 patients with non-small cell lung carcinoma (NSCLC)." (PMID 25222473, 2014).